RN7SL356P (RNA, 7SL, cytoplasmic 356, pseudogene)
Gene: Miscellaneous RNA gene on chromosome 14 (76,967,518 to 76,967,765, reverse strand). Ensembl gene ENSG00000266553.
Homologues: Orthologues: chimpanzee Metazoa_SRP (98% identical). Paralogues in human: RN7SL850P (81% identical), Metazoa_SRP (81% identical), Metazoa_SRP (80% identical), RN7SL279P (80% identical), Metazoa_SRP (79% identical), RN7SL377P (79% identical), RN7SL202P (79% identical), RN7SL32P (79% identical), Metazoa_SRP (78% identical), RN7SL155P (77% identical), RN7SL716P (77% identical), RN7SL48P (75% identical), and 703 more.